IL1A (interleukin 1 alpha)
Diseases named in the same sentence as IL1A in open-access papers (continued):
Sharing a sentence is not in itself a finding about the gene and the disease.
tumor (continued). "Our study has demonstrated that IL1A exhibits potential anti-tumor effects on KIRC; however, interleukin monotherapy has encountered significant limitations in research endeavors over recent years." (PMID 40612864, 2025). "Cancer and stromal cells in the tumor microenvironment, which play a vital role in cancer progression, secrete high concentrations of interleukin-1 alpha (IL-1α) under conditions such as hypoxia and nutrition deprivation." (PMID 40940885, 2025). "Our analysis of the relationship between tumor size and tumor secretions revealed that larger tumors were associated with higher levels of TNF-α, TNF-R2, IL-1α, IFN-α, MIP-1β, and IL-21." (PMID 39923035, 2025). "Prior studies have shown that IL-1α blockade can attenuate tumor-promoting inflammation, suggesting therapeutic potential." (PMID 40940885, 2025). "Malignant cells, tumor-infiltrating immune cells, and stromal cells can express IL1A, which is overexpressed in GC and is closely related to the clinical features of patients with GC." (PMID 40606972, 2025). "We demonstrated that VS-induced SNHL was linked to increased secretion of TNF-α, IL-2R, CD163, eotaxin, and HGF, while larger tumor size was associated with higher levels of TNF-α, TNF-R2, IL-1α, IFN-α, MIP-1β, and IL-21 secretion." (PMID 39923035, 2025). "IL-1α expression was markedly higher in tumours from patients aged ≥64 years (p = 0.021), and in advanced TNM prognostic stages (p = 0.047)." (PMID 41465261, 2025). "Anakinra, an inflammasome recombinant IL1 receptor antagonist, blocks both IL1α and IL1β, showing potential in reducing tumor-related inflammation." (PMID 39766086, 2024). "Since the cellular composition of the TME had been clearly affected by IL-1α, it made sense to assess chemokine levels in tumor tissues." (PMID 38612760, 2024). "Targeting intracellular IL-1α in cancer and/or host cells elicits the most pronounced effect on tumor growth." (PMID 38612760, 2024). "We confirmed that both IL-1α and IL-1β were highly upregulated at the protein level in the tumor-bearing lungs of old mice by ELISA." (PMID 39236155, 2024). "To further confirm the role of cellular immunity in the suppression of 4T1 IL-1α KO-induced tumor growth, we performed a Winn assay." (PMID 38612760, 2024). "Strikingly, still, both IL-1α and IL-1β production by lung MPs were significantly increased in tumor-bearing lungs of old mice than in young mice, suggesting that hematopoietic aging enhances their production." (PMID 39236155, 2024). "Macrophages internalize p-MET, leading to increased levels of IL-1β and IL-6 mRNA and elevated IL-1α secretion, which fosters tumor growth." (PMID 39726601, 2024). "Blocking IL-1β also helped to reduce tumor progression, but combining IL-1α/IL-1β blockade or targeting them both using the IL-1R1 antagonist anakinra most effectively disrupted tumor initiation." (PMID 39236155, 2024). "Engraftment of IL-1α knockout 4T1 cells into immunodeficient NOD.SCID mice resulted in more rapid tumor growth, with increased lung metastasis in comparison to engraftment of 4T1/WT cells." (PMID 38612760, 2024). "It has also been shown that IL-1R signaling is involved in MDSCs expansion, migration and function, and that IL-1α secreted from a tumor can suppress T cell function via promoting MDSCs in the microenvironment of HCC." (PMID 38612760, 2024). "Detailed phenotypic profiling showed that TREM1 myeloid cells were enriched for IL1A, OSM, and IL6 expression compared to other myeloid populations, further supporting the association between BIT tumor epithelium and TREM1 myeloid-derived IL1A and OSM." (PMID 39289380, 2024). "Recent research indicates that PC cells secrete IL-1α to stimulate tumor-promoting fibroblast infiltration through paracrine signaling." (PMID 38634049, 2024).
tumor (continued). "Among the mechanisms that regulate PD-L1 expression, the production of cytokines, such as IL-1a, IL-27, IL-10, and IL-32g, in the tumor microenvironment (TME) can upregulate the expression of PD-L1 on monocytes and tumor cells." (PMID 38543183, 2024). "The existing body of evidence suggests that both tumor- and TME-derived IL-1α can affect tumor development." (PMID 38612760, 2024). "Orthotopical injection of IL-1α knockout (KO) 4T1 cells into BALB/c mice led to a significant decrease in local tumor growth and lung metastases, compared to injection of wild-type 4T1 (4T1/WT) cells." (PMID 38612760, 2024). "Further analysis of the differential expression of IL-1 family and related genes in normal tissues and HPV- and HPV+ tumor tissues revealed that IL-1α, IL-1β, IL1R1, IL1R2, IL1RL1, IL1RAP, IL1F10, IL-18 and CASP1 were highly expressed in HPV- tumors." (PMID 39461030, 2024). "It has been shown that in the TME, dying tumor cells release the inflammatory precursor IL-1α, which, similar to IL-1β, increases tumor invasiveness and angiogenesis." (PMID 38553639, 2024). "Taken together, these results suggest that IL-1α KO cells exhibit a more aggressive phenotype in vitro, which ostensibly should have led to a more rapid tumor growth and extensive metastases in vivo." (PMID 38612760, 2024). "Thus, another goal of this study was to determine whether HIFU treatment causes an influx of immune cells into the tumor area and the expression of pro-inflammatory cytokines: interleukin-1α (IL-1α), interleukin-1β (IL-1β), interferon γ (IFN-γ), and tumor necrosis factor α (TNF-α)." (PMID 39199617, 2024). "Lastly, TAM5, enriched in the primary tumor (PT), exhibited high expression of various immunosuppressive factors, including IL1A, IL1B, IL1RN, and IL6." (PMID 39236316, 2024). "Further analyses identified tumor monocytes as the principal producers of both IL-1β and IL-1α at the RNA and protein levels." (PMID 39030280, 2024). "First, activation of TAMs releases IL‐1α and IL‐1β to act on tumour cells, activating the intracellular NF‐κB pathway, which next exerts a pro‐coagulant effect by affecting NLRP3 inflammatory vesicles." (PMID 38652105, 2024). "Altogether, these results confirmed the critical role of the host immune response in the inhibition of tumor growth in mice inoculated with 4T1 IL-1α KO cells." (PMID 38612760, 2024). "Esc and Zeb1/Snail OE tumors expressed lower levels of gMDSC-recruiting cytokines and chemokines than parental and EV tumor cells, including G-CSF, GM-CSF, IL-1a, and CXCL2." (PMID 38378697, 2024). "For example, IL‐1α a cytokine released by necrotic tumour cells can promote stromal cell proliferation, and stromal endogenous factors secreted by stromal cells counteract the tumour to promote angiogenesis, metastasis and infiltration." (PMID 38652105, 2024). "S8B); this contrasted with mice that received anakinra starting at 1-week post-inoculation, suggesting that inhibiting IL-1α signaling at the precancer stage/during tumor initiation is a unique opportunity to derail lung tumor growth." (PMID 39236155, 2024). "In this study, we show that both tumor- and the TME-derived IL-1α is involved in tumor development in mice." (PMID 38612760, 2024). "Partial EMT can account for the more motile and less adhesive phenotype of IL-1α KO cells, as well as pointing toward a more aggressive and metastatic tumor." (PMID 38612760, 2024). "Further studies are needed to determine the impact of IL-1α and other chemokines and alarmins released during tumor cell pyroptosis in promoting an immunostimulatory environment that elicits antitumor immunity." (PMID 38391959, 2024). "To separate the effects of extracellular vs. intracellular IL-1α on tumor development, we injected 4T1/WT-inoculated BALB/c mice with neutralizing anti-IL-1α antibodies, thereby blocking the effects of extracellular IL-1α." (PMID 38612760, 2024).
tumor (continued). "In mice injected with 4T1/WT cells, tumor growth was apparent by day 15, developing into large tumors by day 30; whereas mice injected with either IL-1α KO clone showed much slower tumor progression." (PMID 38612760, 2024). "The main goal of this study was to evaluate the role of IL-1α expression in tumor cells in the progression of TNBC in mice." (PMID 38612760, 2024). "Blocking this axis with an anti-IL-1α antibody early during tumor initiation not only slowed lung tumor growth but also normalized emergency myelopoiesis in old mice." (PMID 39236155, 2024). "The IL-1 family encompasses interleukins such as IL-1α, IL-1β, IL-33, etc., each of which play multifaceted roles in the regulation of carcinogenesis and tumor progression." (PMID 39483474, 2024). "Remarkably, tumor growth in IL-1Ra KO mice injected with IL-1α KO cells was strongly inhibited, in comparison to injection of 4T1/WT cells, despite the pronounced pro-inflammatory TME phenotype of these mice." (PMID 38612760, 2024). "It has been observed that tumor cells undergo necroptosis after releasing interleukin-1α (IL-1α) to activate dendritic cells (DCs)." (PMID 38546403, 2024). "Regarding the protumor potential, it has been discovered that both IL-1α and IL-1β help with tumor angiogenesis and invasiveness as PCa develops." (PMID 38745115, 2024). "Neutrophils and myeloid-derived suppressor cells were abundant in tumors developing after injection of 4T1/WT cells, whereas more antigen-presenting cells were observed in the tumor microenvironment after injection of IL-1α KO 4T1 cells." (PMID 38612760, 2024). "The expressions of SHISA5, SERPINE1, and IL1A were markedly high in tumor tissues, whereas those of TP53AIP1, ETS2, and FOS were high in the normal tissues." (PMID 38435998, 2024). "Nevertheless, in NOD.SCID mice injected with IL-1α KO cells, the spleens were enlarged, compared to those from 4T1/WT tumor-bearing mice." (PMID 38612760, 2024). "The existing body of evidence indicates that IL-1α production in cancer cells can play a major role in tumor progression." (PMID 38612760, 2024). "Even though these two cytokines comparably transduce signaling, the role of IL-1α has been debated, but IL-1β was shown to promote tumor growth in cancer." (PMID 39201290, 2024). "Transcriptomic profiling of mouse primary BCC tumor-derived organoids following Il1a and Osm combination treatment demonstrated genome-wide changes consistent with those observed in mouse BCC cell line." (PMID 39289380, 2024). "We observed enrichment of pathways associated with cancer, cell proliferation and survival, cytokine network function, cell motility and adhesion after knockout of IL-1α from tumor cells." (PMID 38612760, 2024). "Firstly, we were unable to evaluate the effect of tumor-induced IL-1α on the phenotype and polarization of macrophages in the ESCC microenvironment." (PMID 37998338, 2023). "Using these murine PDGFB-driven (PDGFB mGBM) and Nf1-silenced (Nf1 mGBM) GBM models that show differential myeloid recruitment, we investigated how IL-1α and IL-1β individually contribute to tumor development in vitro and in vivo." (PMID 37733448, 2023). "Surprisingly, in contrast to the extended survival duration of Il1b–/–;Ntv-a mice, the survival time of tumor-bearing Il1a–/–;Il1b–/–;Ntv-a mice was similar to that of the WT;Ntv-a mice." (PMID 37733448, 2023). "Increased expression of IL-1α and IL-1β has been reported in numerous cancers, where their tumor-promoting roles have been established." (PMID 37733448, 2023). "In human breast carcinoma, IL-1α, IL-1β, and IL-1Rα were shown to be highly expressed and found to promote tumor progression." (PMID 37370720, 2023). "Flow cytometric analysis revealed that both rIL‐1α and IL‐1α‐MPs generally increased most of the tumor immune cell populations analyzed compared to saline and Blank MP treatment." (PMID 37206237, 2023).
tumor (continued). "In concert with tumor-produced LIF that expands the quantity of splenic HSPC niche cells, tumor-derived IL-1α induces TNFα expression by HSPCs to alter niche function into favoring increased EMH." (PMID 37134077, 2023). "They found that tumors produced the inflammatory cytokine IL-1α, which was found at increased levels in the circulation of tumor-bearing mice." (PMID 37141182, 2023). "Both IL‐1α and IL‐1β promote tumor angiogenesis and invasion, but IL‐1β has a more prominent role in these processes." (PMID 37547175, 2023). "Lastly both rIL‐1α and IL‐1α‐MPs significantly increased IFNγ, which is a prominent cytokine in anti‐tumor immunity compared to control and Blank MP‐treated mice." (PMID 37206237, 2023). "There is a marked reduction (p < 0.001) in the expression of IL-1α and IL-1β in the tumor tissues of Anakinra treated mice compared to all of the other groups." (PMID 38152619, 2023). "The expression of IL-1α is up-regulated in tumor tissue compared to para-tumor tissues in several cancer types." (PMID 36979463, 2023). "Recent advances in targeting the pro-tumorigenic effects of tumor stroma include the use of IL1α blocking antibodies." (PMID 36757577, 2023). "For example, myCAFs, activated by direct contact with neoplastic cells, reside adjacent to tumor foci, whereas iCAFs, induced by cancer cell-derived factors such as IL-1α and TNFα7,57, are located more distant from tumor cells." (PMID 37394578, 2023). "On the other hand, Nos2 and Il1a, indicative of M1 macrophages, were also upregulated, suggesting a mix of macrophage subtypes within the primary tumor in the wake of irradiation." (PMID 37345658, 2023). "To validate the function of IL1α in promoting tumor growth, cancer metastasis, and macrophage recruitment, we overexpressed IL1α in the 231‐GFP cells and assessed its effects in vitro and in vivo." (PMID 37551997, 2023). "The current study focuses on MDK and IL-1α as two mediators of Schwann cells in tumor cells and CAFs." (PMID 37524695, 2023). "This invasive form of p-FoxM1 upregulates the expression of IL1A/1B, VEGFA, and IL6 by direct activation, recruiting monocytes and promoting the polarization of M2d-like tumor-associated macrophages (TAMs)." (PMID 37968723, 2023). "IL-1α and IL-1β immune-reactivities are predominant in the cytoplasm of the macrophages, lymphocytes, and tumor cells." (PMID 38152619, 2023). "As expected, the risk factors ANG and IL1A showed the highest expressions in the necrosis-related area (PAN and PNZ) within the tumor zone." (PMID 37891828, 2023). "More importantly, overexpression and knockdown experiments showed that IL1α controlled the expression of IL1β and IL8 in TNBC 231‐GFP cells, which indicates IL1α as a critical cytokine in macrophage‐stimulated tumor progression." (PMID 37551997, 2023). "We identify tumor produced IL-1α and leukemia inhibitory factor (LIF) acting on splenic HSPCs and splenic niche cells, respectively." (PMID 37134077, 2023). "Cancer cells release pro-inflammatory factors such as IL-6, IL-1a, TGF-β, and TNF-ɑ to activate cancer-associated fibroblasts (CAF) into iCAF, and radiation induces tumor cells to secrete large amounts of cytokines with radioresistance." (PMID 37322433, 2023). "Serotonin has been shown to be a growth factor for multiple types of human tumor cells and stimulates collagenase production by uterine smooth muscle via IL1-α." (PMID 37445642, 2023). "In the study by Barisas and colleagues, deletion of IL1A from the tumor cells decreased TNFα and total splenic myeloid progenitors." (PMID 37141182, 2023). "Taken together, these results revealed that overexpression of IL1α enhanced tumor growth, cancer metastasis, and macrophage infiltration into xenografted tumor sites." (PMID 37551997, 2023). "In vitro, transcription of satDNA was induced in lung fibroblasts in response to TGFβ, IL1α, matrix stiffness, direct contact with tumor cells and treatment with chemotherapeutic drugs." (PMID 36635266, 2023).
tumor (continued). "More importantly, immunohistochemical (IHC) staining showed that the overexpression of IL1α significantly increased the infiltration of CD163+ or CD204+ macrophages into the xenografted tumor tissues by 4.8‐ and 5.1‐fold, respectively." (PMID 37551997, 2023). "This positive correlation suggest that a high expression of IL1α increased the infiltration of macrophages, which further facilitated tumor progression." (PMID 37551997, 2023). "Several studies have shown that IL-1A expression is higher in a variety of tumor tissues than in paracancerous tissues." (PMID 37722877, 2023). "Treatments that lower IL‐1RA levels can tilt IL‐1α toward IL‐1RA homeostasis, enhancing tumor senescence and improving the efficacy of chemotherapy." (PMID 37547175, 2023). "When stimulated by pro-inflammatory cytokines such as IL-1α, IL-1β, and tumor necrosis factor α, CAFs tend to shift towards a senescent state, inhibiting tumor cell apoptosis and promoting tumor cell dissemination." (PMID 38013358, 2023). "Although IL-1α and IL-1β both signal through the same ubiquitously expressed receptor (IL-1R1) on all cells, the resulting effects on tumor biology can be distinct and tissue specific." (PMID 37733448, 2023). "Both rIL‐1α and IL‐1α‐MP‐treated mice showed similar delays in tumor growth and similar increases in tumor‐infiltrating CD3+ T cells, macrophages, and dendritic cells." (PMID 37206237, 2023). "Interleukin‐1 alpha (IL‐1α) is a pro‐inflammatory cytokine that can activate immune effector cells and trigger anti‐tumor immune responses." (PMID 37206237, 2023). "The group of alarmins (HGMB1, IL‐1α, S100 proteins and IL‐33) showed a different role, promoting or inhibiting tumour progression, depending on the type of the tumour, stage and their localization." (PMID 35344301, 2022). "Secondly, tumor cells will also produce IL-1α, which will stimulate CAFs to keep an inflammatory state within the TME by promoting their production of inflammatory factors." (PMID 36499246, 2022). "In an array of studies, they show that IL-1α present in the ex vivo culture media of murine tumour cells was responsible for the pre-conditioning of CAFs, resulting in polarisation to an inflammatory iCAF phenotype." (PMID 36313650, 2022). "Investigating the effect of microRNA‐22 on HCC, researchers detected an increased expression of IL‐1α in tumour‐adjacent tissues in the male subset, inversely correlated with the expression of oestrogen receptor α." (PMID 35838746, 2022). "Pro-inflammatory cytokines such as IL-1α and IL-1β are found within the HNSCC tumor microenvironment and have been linked to tumor development and spread." (PMID 36143043, 2022). "Pharmacological inhibition of IL-1α-NF-kB signaling in orthotopic HCC1954 xenografts synergistically reduced tumor size in mice treated with paclitaxel." (PMID 35626710, 2022). "IL-1α and IL-1β are cancer-promoting and drive angiogenesis, tumor progression, and tumor aggressiveness." (PMID 35565306, 2022). "Concentration of pro‐inflammatory and pro‐angiogenic cytokines including IL‐1a, IL‐2, IL‐6, IL‐10, IL‐12, and IL‐17A, in peripheral blood of tumor bearing mice receiving anti‐MUC1 nanobody was significantly lower compared to the PBS receiving group." (PMID 34694686, 2022). "In contrast, systemic administration of recombinant IL-1A protein exerted an anti-tumor effect by directly activating T cells." (PMID 36071472, 2022). "The location of released IL-1A is therefore crucial to understanding how it contributes to tumor growth." (PMID 36071472, 2022). "While the membrane-associated IL-1α is mainly immunostimulatory, IL-1β that is secreted into the TME is mainly pro-inflammatory and promotes tumorigenesis, tumor invasiveness, and immunosuppression." (PMID 36074553, 2022). "Next, considering the potential tumor suppressor role of EPHX3 in HNSCC, we examined the association between EPHX3 and CD274, IL1B, IL1A, PDCD1, and PDCD1LG2." (PMID 35401746, 2022).